A2M (alpha-2-macroglobulin)
Diseases named in the same sentence as A2M in open-access papers (continued):
Sharing a sentence is not in itself a finding about the gene and the disease.
ovarian carcinoma (4 papers, 2011 to 2016). A malignant neoplasm originating from the surface ovarian epithelium. "We previously reported expression of cysteine protease cathepin B (CTSB), serpin peptidase inhibitor, clade B, member 11 (SERPINB11) and alpha 2 macroglobulin (A2M) in ovarian tissue from hens with ovarian cancer." (PMID 22496782, 2012). "In chickens, A2M has been identified and characterized biochemically, but little is known of its functional role(s) in the oviduct, hormonal regulation of expression or its expression in ovarian carcinomas in chickens." (PMID 21978460, 2011). "Results of this study indicate that A2M is a novel estrogen-stimulated gene during development of the chicken oviduct and that it may be an initial candidate gene for further study of the development of epithelial ovarian cancer in hens." (PMID 21978460, 2011). "Indeed, CTSB, SERPINB11, A2M, and PTN are genes that we reported to be most abundant in the GE of ovarian cancers in laying hens." (PMID 23843947, 2013). "In addition, several proteins which previously have been shown to be elevated in the serum of ovarian cancer patients such as Chitinase-3-like protein 1(CHI3L1) [Rsc = 4.5], Haptoglobin (HP) [Rsc = 4.0] and Alpha-2-macroglobulin (A2M) [Rsc = 2.5] were elevated in CR." (PMID 27470985, 2016).
periodontitis (4 papers, 2008 to 2022). An acute or chronic inflammatory process that affects the tissues that surround and support the teeth. "In Aurer study on different groups including chronic periodontitis patients, healthy group, and patients with tooth loss showed that in addition to TNF-α, salivary levels of other inflammatory factors such as C3, CRP, and α-2M were lower in periodontitis group compared to other groups." (PMID 29238418, 2017). "It is known for example that the level of alpha-2-macroglobulin, alpha-1-antitripsin, elastase and also albumin in saliva may be good indicators of gingivitis and/or periodontitis." (PMID 19424479, 2008).
pneumonia (4 papers, 2023 to 2025). An acute, acute and chronic, or chronic inflammation focally or diffusely affecting the lung parenchyma, caused by an infection in one or both of the lungs (by bacteria, viruses, fungi, or mycoplasma.). "In Baladi goats with pneumonia and healthy control group, PCR-DNA sequencing revealed SNPs linked to pneumonia susceptibility and resistance in immunological genes (SLC11A1, CD-14, CCL2, TLR1, TLR7, TLR8, TLR9, defensin, SP110, SPP1, BP1, A2M, ADORA3, CARD15, IRF3, and SCART1)." (PMID 40221769, 2025). "The immune genes’ mRNA levels in goats (SLC11A1, CD-14, CCL2, TLR1, TLR7, TLR8, TLR9, defensin, SP110, SPP1, BP1, A2M, ADORA3, CARD15, IRF3, and SCART1) varied between the healthy and infected goats with pneumonia." (PMID 40711280, 2025). "Through PCR-DNA sequencing in Baladi goats with and without pneumonia, SNPs linked to pneumonia susceptibility and resistance were discovered in the immunological (SLC11A1, CD-14, CCL2, TLR1, TLR7, TLR8, TLR9, defensin, SP110, SPP1, BP1, A2M, ADORA3, CARD15, IRF3, and SCART1) genes." (PMID 40711280, 2025). "The levels of immunological genes (SLC11A1, CD-14, CCL2, TLR1, TLR7, TLR8, TLR9, defensin, SP110, SPP1, BP1, A2M, ADORA3, CARD15, IRF3, and SCART1) vary in goats with and without pneumonia." (PMID 40221769, 2025). "Real-time PCR was conducted to quantify the expression levels of immunological markers (SLC11A1, CD-14, CCL2, TLR1, TLR7, TLR8, TLR9, β defensin, SP110, SPP1, BP1, A2M, ADORA3, CARD15, IRF3, and SCART1) in Baladi goats with and without pneumonia resistance." (PMID 36977224, 2023).
amyloidosis (3 papers, 2013 to 2025). A disorder characterized by the localized or diffuse accumulation of amyloid protein in various anatomic sites. "Associations have been identified between elevated serum α2M and dialysis related amyloidosis." (PMID 34458849, 2021). "In the SMC-calc vs. SMC comparison based on limma, clusters related to high-density lipoprotein (HDL) assembly (PF4V1, APOA1, LPXN, AFP, A2M, and MMP1) and amyloidosis (CX3CL1, APOE, PLIN3, TGFBI, and CH25H) were identified." (PMID 41301179, 2025).
autoimmune disease (3 papers, 2016 to 2025). A disorder resulting from loss of function or tissue destruction of an organ or multiple organs, arising from humoral or cellular immune responses of the individual to their own tissue constituents. "Changes in the glycosylation of Alpha-2-macroglobulin and Alpha-2-HS-glycoprotein have been associated with cancer and autoimmune diseases." (PMID 26999365, 2016). "Alpha-2-macroglobulin (A2M) and vitronectin (VTN), both involved in coagulation and fibrosis, represent targets for thrombotic and vascular complications in autoimmune diseases." (PMID 40142826, 2025).
dementia (3 papers, 2022 to 2024). Loss of intellectual abilities interfering with an individual's social and occupational functions. "Our analysis validates the interdependence of AD, dementia, and Parkinson’s disease through various common genes (i.e., A2M, ABCA7, PLAU, PSEN2, and MPO)." (PMID 38790243, 2024).
hepatocellular carcinoma (3 papers, 2015 to 2024). A malignant tumor that arises from hepatocytes. "Association of cell surface GRP78 with α2M* promotes the invasion and metastasis of HCC in hepatocellular carcinoma cell lines QGY-7703 and PLC by stimulating the translocation of GRP78 from the cytosol to plasma." (PMID 25958313, 2015). "In conjunction with α2M*, membrane-associated GRP78 in hepatocellular carcinoma (HCC) cells is capable of interacting directly with Src, a tyrosine kinase, stimulating its phosphorylation and further facilitating the interaction between Src and epidermal growth factor receptor (EGFR)." (PMID 38646439, 2024). "In this article, we stimulated hepatocellular carcinoma cell lines PLC and QGY-7703 with α2M* and demonstrated that c-Src is the surrogate in cell surface GRP78 induced tumor invasion and metastasis." (PMID 25958313, 2015).
Hepatopathy (3 papers, 2019 to 2024). "Hepatopathy has been shown to cause a reduction in plasma alpha 2 macroglobulin." (PMID 38813463, 2024). "Serum biochemical parameters, such as AST and ALT, show abnormally high values in rats with hepatopathy, while serum concentrations of α2M are lower than in normal rats." (PMID 32257902, 2019). "Individual data were then evaluated to clarify the degree that hepatopathy affects the synthesis of α2M." (PMID 32257902, 2019). "The degree of hepatopathy affecting the synthesis of α2-macroglobulin (α2M) as an acute phase protein in rats was investigated." (PMID 32257902, 2019). "In conclusion, synthesis of α2M in rats is evidently suppressed in the severe stages of hepatopathy." (PMID 32257902, 2019). "From these results, the synthesis of α2M was considered to be inhibited in severe hepatopathy stages." (PMID 32257902, 2019). "Evaluation of the degree of inflammation using serum concentrations of α2M may therefore give inaccurate results when assessing candidate substances that induce hepatopathy." (PMID 32257902, 2019). "The effects of hepatopathy on synthesis of α2M in rats could be evaluated after single administration of turpentine oil." (PMID 32257902, 2019). "We evaluated how the hepatopathy induced by galactosamine affected the synthesis of α2M in rats." (PMID 32257902, 2019). "Estimation of α2M as an inflammatory marker will therefore be need to be carefully evaluated in non-clinical studies, particularly toxicological studies that use high dosages or evaluate substances that induce severe hepatopathy." (PMID 32257902, 2019). "The synthesis of α2M in rat liver was largely sustained until severe hepatopathy." (PMID 32257902, 2019). "Thus, the cut-off value for reductions in the serum concentration of α2M in rats with hepatopathy was determined from receiver-operating characteristic (ROC) curve analysis." (PMID 32257902, 2019). "In relation to non-standard-of-care biomarkers and indices of liver dysfunction, those who died had higher serum hsCRP, serum NT-proBNP, serum AST/ALT, serum haptoglobin, serum hyaluronic acid and serum alpha-2 macroglobulin, but a lower serum, albumin." (PMID 39402659, 2024). "In relation to non-standard-of-care biomarkers and indices of liver dysfunction, those with an incident MACE had higher serum NT-proBNP, serum aspartate/alanine transferase ratio (AST/ALT), serum hyaluronic acid (ug/L) and serum alpha-2 macroglobulin (g/L)." (PMID 39402659, 2024). "In relation to non-standard-of-care biomarkers and indices of liver dysfunction, those who died had higher serum NT-proBNP, serum AST/ALT, serum hyaluronic acid and serum alpha-2 macroglobulin, but a lower serum albumin." (PMID 39402659, 2024). "In relation to non-standard-of-care biomarkers and indices of liver dysfunction, those with an incident MACE had higher serum NT-proBNP, serum AST/ALT, serum hyaluronic acid and serum alpha-2 macroglobulin." (PMID 39402659, 2024).
multiple sclerosis (3 papers, 2013 to 2022). A progressive autoimmune disorder affecting the central nervous system resulting in demyelination. "Previous studies have also revealed that changes in the glycosylation of A2M are associated with systemic lupus erythematosus and multiple sclerosis." (PMID 36698894, 2022). "However, we found no relation of PREP activity to the levels of α2M or effect of reducing agents, like DTT, on enzymatic activity in multiple sclerosis samples or in this study (data not shown)." (PMID 26420028, 2015).
prion disease (3 papers, 2009 to 2023). A transmissible disease that is caused by a protein that is able to induce abnormal folding of normal cellular proteins, leading to characteristic spongiform brain changes, which are associated with neuronal loss without an inflammatory response. "α2M can bind to a range of endogenous disease-associated proteins including the amyloid β peptide (Aβ1–42), prion proteins and β2-microglobulin, which are the main components of deposits found in Alzheimer’s disease (AD), spongiform encephalopathies and dialysis-related amyloidosis, respectively." (PMID 23353684, 2013). "Moreover, α2M is found to be co-localized in vivo with amyloid deposits in AD and the spongiform encephalopathies." (PMID 23353684, 2013).
Stroke (3 papers, 2018 to 2023). Sudden impairment of blood flow to a part of the brain due to occlusion or rupture of an artery to the brain. "Hence, in clinical diagnosis and treatment, serum marker tests for A2M, LBP, CTSG, CST3, and FABP1 should be prioritized in patients with a high suspicion of stroke for early detection and timely intervention." (PMID 38090270, 2023).
thrombosis (3 papers, 2018 to 2022). "In a proteomic study of plasma micro-particles, alpha-2-macroglobulin was also found upregulated in patients after deep venous thrombosis in comparison to healthy subjects." (PMID 29665821, 2018). "α2M was significantly lower in the thrombosis group, and FVIII and VWF were significantly higher." (PMID 36248875, 2022).
viral infections (3 papers, 2012 to 2023). "Additionally, the immunomodulatory genes transmembrane protein 2 (IFITM2) and alpha-2 macroglobulin (A2M) were both upregulated in regions of viral infection." (PMID 36968839, 2023). "Previous work has identified syntenin of the shrimp Penaeus monodon (Pm) as a dynamic responder to white spot syndrome virus (WSSV) infection through its interaction with alpha-2-macroglobulin (alpha2M), which plays an important role in the immune defense mechanisms of viral infections of shrimps." (PMID 22571704, 2012). "Herein, we verified that α2M, but not LF, markedly upregulated IFNAR1 under viral infections or treated with rLRPAP1." (PMID 37743411, 2023).
Arthritis (2 papers, 2021 to 2023). Inflammation of a joint. "Among ADAMTS proteases involved in arthritis, α2M was shown to inhibit both ADAMTS4 and ADAMTS5 in a dose-dependent manner." (PMID 34268335, 2021). "In the context of arthritis, α2M was found in similar concentrations as TIMP3 in the synovial fluid of joints and it rapidly bound to collagenase." (PMID 34268335, 2021). "However, since α2M has many functions it is unclear to what extent the arthritis-protective effects can be related to the direct inhibition of ADAMTS proteases or the interaction of α2M with inflammatory cytokines, such as IL-1β or tumor necrosis factor TNFα." (PMID 34268335, 2021). "In addition, the cartilage oligomeric matrix protein (COMP)-processing activities of ADAMTS7 and ADAMTS12 were inhibited by α2M, suggesting that dysregulation of the ADAMTS7 and ADAMTS12 protease activity through α2M could be involved in arthritis." (PMID 34268335, 2021).
asthma (2 papers, 2017 to 2022). "A2M is a cytokine transporter and protease inhibitor of trypsin, thrombin, and collagenase, already reported to be involved in severe asthma mechanisms such as regulation of airway remodeling." (PMID 35453511, 2022).
autism (2 papers, 2019 to 2022). Persistent deficits in social interaction and communication and interaction as well as a markedly restricted repertoire of activity and interest as well as repetitive patterns of behavior. "Besides, three proteins i.e., A2M, SERPINA1, and SERPIND1 were also associated with complement and coagulation cascades in the present study, indicating that complement system and coagulation cascades may be involved in the pathogenesis of autism." (PMID 30941018, 2019).
chronic heart failure (2 papers, 2012 to 2023). "Apolipoprotein E, tropomyosins, alpha-2 macroglobulin, complement 3, creatin kinase B and ceruloplasmin have been also described as biomarkers for chronic heart failure." (PMID 22384053, 2012).
Chronic Lymphocytic Leukemia (2 papers, 2020 to 2022). "A2M also participates, with IgG molecules, in formation of immune complexes that generate aggregated/hexameric structures (A2M-IgG-hexamers) and activate the classical pathway (CP) of the complement system in patients with Chronic Lymphocytic Leukemia (CLL)." (PMID 36119042, 2022).
colorectal cancer (2 papers, 2021 to 2025). A primary or metastatic malignant neoplasm that affects the colon or rectum. "Evidence suggests that HSPA4, HSP90AB1, DNTM1, RPS27, FTL, NCL, A2M are implicated in the pathogenesis and progression of colorectal cancer, positioning them as potential prognostic biomarkers for the onset of metastasis." (PMID 41319168, 2025). "Previous reports stated that α2M isolated from patients with colorectal cancer contained more α2,6Sia, GlcNAc and mannose residues, as well as more multiantennary complex type n-glycans, compared to α2M isolated from healthy participants." (PMID 34071388, 2021).
diabetic kidney disease (2 papers, 2021 to 2023). Progressive kidney disorder caused by vascular damage to the glomerular capillaries, in patients with diabetes mellitus. "This study showed that α2M was specifically upregulated in disease and its higher expression was associated with poorer kidney outcomes, suggesting the importance of α2M* signaling may also be relevant to non-diabetic kidney disease." (PMID 36909183, 2023).
endothelial dysfunction (2 papers, 2018 to 2023). In vascular diseases, endothelial dysfunction is a systemic pathological state of the endothelium (the inner lining of blood vessels) and can be broadly defined as an imbalance between vasodilating and vasoconstricting substances produced by (or acting on) the endothelium. "In our study, among differentially expressed proteins were PLG, SERPING1, SERPINC1, APOA2, FGB, A2M, which are related to endothelial dysfunction, coagulation processes and pro-atherogenic alteration mechanisms." (PMID 29755368, 2018).
fatty liver disease (2 papers, 2022 to 2026). A reversible condition wherein large vacuoles of triglyceride fat accumulate in liver cells via the process of steatosis. "Liver enzyme activity (ALT, AST, GGT), total bilirubin, lipids fractions, apolipoprotein A1 (ApoA1), α-2-macroglobulin (α2M), haptoglobin (Hp), fasting blood glucose, and fasting insulin are used to generate liver steatosis scores." (PMID 35268466, 2022).
focal segmental glomerulosclerosis (2 papers, 2023 to 2025). A renal disorder characterized by sclerotic lesions in the glomeruli. "Recent research shows that high A2M mRNA expression of glomerular tissue is associated with a longer time to reach complete remission of proteinuria and poor prognosis of patients with focal segmental glomerulosclerosis." (PMID 37033921, 2023). "Indeed, two focal segmental glomerulosclerosis (FSGS) patient subgroups were identified based on alpha‐2 macroglobulin (A2M) expression, which was associated with proteinuria remission rates and long‐term renal outcomes." (PMID 40537978, 2025).
glaucoma (2 papers, 2017 to 2021). Increased pressure in the eyeball due to obstruction of the outflow of aqueous humor. "Among the identified proteins significantly altered in glaucoma, eight were further studied using semi-targeted or targeted approaches, showing higher levels of ALB, APOC3, CysC, TIMP2, A2M, PGTDS, and ENPP2, and lower levels of SOD1, in POAG patients compared to control subjects." (PMID 34439995, 2021).
heart failure (2 papers, 2021 to 2023). Inability of the heart to pump blood at an adequate rate to meet tissue metabolic requirements. "Finally, α2M* also prevented aggLDL-induced cardiac damage evidenced by a decreased level of Gal-1 and Gal-3, key mediators of cardiac lipotoxicity and heart failure." (PMID 34203120, 2021). "This evidence suggest that α2M* would have an important role as an insulin sensitizing agent in the heart, as proposed by other studies about patients with metabolic disturbances and heart failure." (PMID 34203120, 2021).
Hepatitis (2 papers, 2009 to 2020). Inflammation of the liver. "Therefore, reduced expression of α2M in asymptomatic WD patients may indicate blunted acute phase response to early stage of hepatitis induced by copper toxicity." (PMID 20556197, 2009).
Hypoalbuminemia (2 papers, 2019 to 2024). The concentration of albumin in the blood circulation is below the lower limit of normal. "Haptoglobin and ceruloplasmin increased as acute phase reaction proteins; alpha-2 macroglobulin increased in a compensatory manner to maintain plasma colloid osmotic pressure due to hypoalbuminemia." (PMID 31357953, 2019). "This was of particular interest as the A2M protein plays a central role in nephrotic patients with hypoalbuminemia by preserving intravascular oncotic pressure as it does not pass through the damaged slit diaphragm due to its high molecular weight." (PMID 39125467, 2024).
ischemic stroke (2 papers, 2019 to 2021). A stroke disorder caused by obstruction of blood flow to the brain, due to thrombotic (local blood clot formation) or embolic (due to a blood clot or other material traveling from another site) event. "Alpha-2-macroglobulin (A2MG), complement C1q subcomponent subunit B (C1QB), complement C1r subcomponent (C1R), and histidine-rich glycoprotein (HRG) were significantly upregulated by 2.21-, 2.15-, 2.24-, and 2.16-fold, respectively, in the ischemic stroke group as compared to the control group." (PMID 34912031, 2021).
lung adenocarcinoma (2 papers, 2022 to 2024). A carcinoma that arises from the lung and is characterized by the presence of malignant glandular epithelial cells. "A2M was shown to play a role in activating the epithelial–mesenchymal transition (EMT) and promoting metastasis in lung adenocarcinoma." (PMID 38612805, 2024). "Moreover, bioinformatics analyses suggest that both A2M and ADAMTS1 expressions are correlated with more aggressive phenotypes of lung adenocarcinoma." (PMID 38612805, 2024).